IL11 (interleukin 11)
Diseases named in the same sentence as IL11 in open-access papers (continued):
Sharing a sentence is not in itself a finding about the gene and the disease.
gastric cancer (continued). "IL11: Although belonging to the IL6 cytokine family and known for its pro-tumorigenic roles in lung and gastric cancers our results represent the first report of its dysregulation in cSCC." (PMID 41438693, 2026). "H. pylori-induced IL-6/IL-11 driving JAK/STAT3 activation plays a major role in the development and progression of gastric cancer." (PMID 40462044, 2025). "Surprisingly, expression of YAP1, STAT3, IL11, or IL6 mRNA transcripts remained comparable across the molecular subtypes of gastric cancer." (PMID 37957015, 2024). "We used this dataset to evaluate the expression patterns of YAP1, STAT3, IL11, IL6, TEAD1, IL6ST, and IL11RA in gastric cancer patients within the four TME subtypes." (PMID 37957015, 2024). "Interestingly, we also found that proinflammatory cytokines (IL-6, IL-11) were rapidly induced after carcinogen exposure and maintained a high level in NOC-transformed and gastric cancer cells." (PMID 32041943, 2020). "Our current research has identified OLC8 as a novel oncogenic lncRNA in IL‐11/STAT3 signaling, and OLC8 may constitute a potential target for gastric cancer intervention." (PMID 31273847, 2019). "Puma and Bad were not altered by treatment with an IL11 Ra mutein antagonist in a mouse model of gastric cancer, however we demonstrated their induction in response to IL11Rα Ab combination treatment with doxorubicin chemotherapy." (PMID 28186993, 2017). "Not surprisingly, enhanced expression of IL‐11 could increase STAT3 activation to favor gastric cancer development." (PMID 31273847, 2019). "Studies have reported pro-tumourigenic roles for IL11 in several epithelial cancers, including breast and colorectal cancer and one recent study highlighted a predominant role for IL11 rather than IL6 in mediating gastric cancer." (PMID 28186993, 2017).
pulmonary fibrosis (43 papers, 2005 to 2026). Chronic progressive interstitial lung disorder characterized by the replacement of the lung tissue by connective tissue, leading to progressive dyspnea, respiratory failure, or right heart failure. "In a therapeutic application, HbFs loaded with mRNA encoding an interleukin-11 single-chain fragment variable (IL-11 scFv) were administered in a murine model of bleomycin-induced pulmonary fibrosis." (PMID 42284495, 2026). "Taken together, these data indicate that the loss of IL11-signaling in AT2 cells prevents the development of lung fibrosis." (PMID 39358385, 2024). "The HPS1 deficiency-induced pulmonary fibrosis phenotype can be mediated by the TGF-β -IL-11 axis, and iNOS also plays a pivotal role in regulating the expression and secretion of IL-11 in activated lung fibroblasts." (PMID 39457053, 2024). "In contrast, IL11 deficient strains were protected from fibrosis development in several murine fibrosis models, including the bleomycin models of lung fibrosis and cardiac fibrosis." (PMID 38455057, 2024). "As a result of these disease associations, the IL‐11 axis is currently being targeted by clinical‐stage antibodies for pulmonary fibrosis." (PMID 38023717, 2023). "The interleukin 11 (Il11) gene that encodes a protein with a role in female fertility and inflammation-induced pulmonary fibrosis has a large number of experimentally validated PP flipons (indicated by black rectangles) with c-mRS matches." (PMID 36902315, 2023). "This autocrine and self-amplifying process is accompanied by increased fibroblast migration and invasion: IL11 is specifically associated with invasive fibroblasts in idiopathic pulmonary fibrosis (IPF)." (PMID 38054591, 2023). "TGF-β1/IL-11/MEK/ERK signaling can mediate aging-related pulmonary fibrosis in a Bmi-1-deficient model of premature aging." (PMID 36845967, 2023). "We previously found that p16 knockout (p16−−) rescues senescence‐associated pulmonary fibrosis (SAPF) in a premature senescence mouse model through down‐regulation of the TGF‐β1/IL‐11/MEK/ERK pathway." (PMID 37345264, 2023). "Two models of IL-11 and bleomycin-induced lung fibrosis associated to PH were used in Tie2-GFP transgenic mice to evaluate the contribution of IL-11 and endothelial cells to pulmonary artery remodeling." (PMID 36376885, 2022). "Regarding IL-11, its upregulation and overexpression in the lungs is usually linked with viral infections, including SARS-CoV-2, and IL-11 induces lung fibrosis and epithelial dysfunction." (PMID 34831321, 2021). "In the human lung, IL-11 upregulation has been associated with viral infections and a range of fibroinflammatory diseases, including idiopathic pulmonary fibrosis." (PMID 33262481, 2020). "In addition, our results showed that AS-IV treatment significantly reduced the expression of inflammatory factors TGF-β and IL-11 closely associated with pulmonary fibrosis, which is consistent with previous studies." (PMID 41224967, 2025). "Pharmacological companies may soon begin clinical trials of anti-IL-11 therapies on patients with idiopathic pulmonary fibrosis, a severe lung disease sharing several risk factors with COVID-19." (PMID 33262481, 2020). "Furthermore, IL11 was recently implicated in cardiovascular and lung fibrosis." (PMID 33047019, 2020). "Anti-IL-11 antibody is effective in preventing bleomycin-induced lung fibrosis in mice and antibodies to IL-11 are now in development for treating IPF and other fibrotic diseases." (PMID 40554265, 2025). "Emerging evidence suggests that IL‐11 plays a significant role in various lung diseases, with its involvement recently demonstrated in idiopathic pulmonary fibrosis, and its impact on other lung pathologies gradually being uncovered." (PMID 40673604, 2025).
pulmonary fibrosis (continued). "Following nebulization, the LNPs effectively deliver IL‐11 scFv mRNA into the lungs and produce antibody to neutralize IL‐11, significantly ameliorating lung fibrosis through suppression of fibroblast activation and ECM deposition." (PMID 41211661, 2025). "Similar results were observed in arterial remodeling, Marfan syndrome, and pulmonary fibrosis, which shows the influence of IL-11 on fibrosis." (PMID 38392279, 2024). "We previously discovered an important role for IL11 in lung fibrosis, mediated via its profibrotic activity in lung fibroblasts and IL11 expression was confirmed in diseased fibroblasts in the current study." (PMID 39358385, 2024). "In IPF patients, IL11 expression levels and disease progression correlate inversely implying the close relevance of this cytokine and lung fibrosis." (PMID 38455057, 2024). "Comparative expression analysis demonstrated that IL11 transcripts are significantly upregulated in patients with fibrotic diseases such as cardiac fibrosis or Idiopathic Pulmonary Fibrosis (IPF)." (PMID 38455057, 2024). "In 2019, two contemporaneous manuscripts appeared on BioRxiv describing a role for IL11 in lung fibrosis." (PMID 38054591, 2023). "With regards to the IL‐11/IL‐11R signaling axis, an anti‐IL‐11R antibody is under evaluation in clinical trials as a treatment of pulmonary fibrosis." (PMID 38023717, 2023). "It is thought that gene mutation-driven AEC dysfunction in HPS causes IL11 secretion, autocrine AEC EMT and paracrine activation of fibroblasts, leading to lung fibrosis." (PMID 38054591, 2023). "The manuscript from our laboratory on IPF followed on from understandings of IL11 in our cardiac studies, whereas the identification of IL11 as a driver of lung fibrosis in Hermansky Pudlak syndrome (HPS) came about from unbiased RNA-seq screening." (PMID 38054591, 2023). "Previously, we demonstrated that aging‐related pulmonary fibrosis was correlated with the IL‐11 signalling pathway in prematurely aging mice." (PMID 37345264, 2023). "Bioinformatics analysis disclosed that both WNT5A and IL11 were involved in pulmonary fibrosis idiopathic disease and functional assays confirmed their association with profibrotic cell responses." (PMID 37545510, 2023). "Recombinant mice (rm)IL-11 induced lung fibrosis and PH in Tie2-GFP mice, activating in vivo EnMT as a contributor of pulmonary artery remodeling and lung fibrosis." (PMID 36376885, 2022). "We found that pulmonary Sirt1 and serum vitamin D decreased with physiological aging, activating TGF‐β1/IL‐11/MEK/ERK signaling, and promoting senescence‐associated pulmonary fibrosis." (PMID 35906886, 2022). "Recent findings have highlighted the role of IL-11 in different fibrotic diseases including cardiac and pulmonary fibrosis." (PMID 36376885, 2022). "A recent study has shown that therapeutic targeting of IL-11 can reduce pulmonary fibrosis and inflammation, while another showed that blocking IL-11 signaling has anti-inflammatory effects, suggesting a complex role for IL-11 in sustained lung inflammation." (PMID 36417363, 2022). "Pharmacological inhibition of IL11 or fibroblast-specific blockade of IL11 signaling reduced fibroblast invasion in vitro and reversed pulmonary fibrosis and inflammation in a murine model of IPF." (PMID 35883698, 2022). "Neutralization of IL-11 was shown to reduce pathological fibrosis in murine models of liver, cardiovascular, and lung fibrosis." (PMID 35085231, 2022). "The NP-mediated amelioration of pulmonary fibrosis was associated with suppression of TGF-β1/SMAD2 and IL-11/ERK signaling pathways as evidenced by Western blotting analysis." (PMID 35731866, 2022). "Pulmonary Sirt1 and serum vitamin D (VD) decrease with physiological aging, activating TGF‐β1/IL‐11/MEK/ERK (TIME) signaling and promoting senescence‐associated pulmonary fibrosis (SAPF)." (PMID 35906886, 2022).
pulmonary fibrosis (continued). "In this work, we first demonstrated the use of inhalable NPs incorporating siRNA to block IL-11 signaling in a preclinical model of pulmonary fibrosis and showed great therapeutic potential of this strategy for repairing injured lung tissues." (PMID 35731866, 2022). "We ended studying the effect of IL-11 inducing pulmonary hypertension and the role of IL-11 gene silencing as a therapeutic target in different animal models of pulmonary fibrosis and pulmonary hypertension." (PMID 36376885, 2022). "To investigate the signaling pathways pivotal for IL-11–driven pulmonary fibrosis, we assessed the activation status of SMAD2, ERK, and STAT3 by Western blotting of lung homogenates from the PBS-treated group, siIL11@PPGC NP–treated group, or healthy controls." (PMID 35731866, 2022). "Similar to pulmonary fibrosis, inhibiting IL11 signaling suppresses the phosphorylation of Erk, thereby reducing liver fibrosis in NASH mice." (PMID 34853322, 2021). "We show that IL11 signaling in Il11−/− mice is important for qualitative fibrotic phenotypes in fibroblasts in vitro and lung fibrosis in vivo." (PMID 34239012, 2021). "Early and late treatment with anti-IL-11 antibodies in bleomycin-challenged mice not only prevented but also reversed established pulmonary fibrosis and specifically reduced pulmonary ERK and SMAD signaling." (PMID 33262481, 2020). "In mice, therapeutic targeting of IL-11 with antibodies can arrest and reverse bleomycin-induced pulmonary fibrosis and inflammation." (PMID 33262481, 2020). "Our results showed that NAC treatment significantly inhibited TGF-β1/IL-11/MEK/ERK signaling to prevent pulmonary fibrosis in Bmi-1−/− mice." (PMID 31959867, 2020). "Initially thought of as a protective cytokine, IL-11 is now increasingly recognized as an important determinant of lung fibrosis, inflammation, and epithelial dysfunction." (PMID 33262481, 2020). "Consequently, antibodies targeting IL‐11 or the IL‐11R are in clinical trials as drug candidates for treating lung fibrosis and nonalcoholic steatohepatitis." (PMID 39673075, 2025). "We speculate that while below the detection threshold of the experimental approaches used, IL11 production at the local tissue environmental might contribute to the development of murine lung fibrosis induced by bleomycin." (PMID 38455057, 2024). "We next sought to determine whether the observed IL11 mRNA elevation in human disease settings can be corroborated by the murine model of bleomycin-induced pulmonary fibrosis." (PMID 38455057, 2024). "Both WNT5A and IL11 related canonical pathways were selected and two canonical pathways were found in common between the four transduced cell lines: Cardiac Hypertrophy Signaling and Pulmonary Fibrosis Idiopathic Signaling." (PMID 37545510, 2023). "It was concluded that IL-11 has rather detrimental than beneficial effects in a variety of murine disease models, including non-alcoholic steatohepatitis, cardiovascular fibrosis, idiopathic pulmonary fibrosis and fibrotic lung disease." (PMID 37061565, 2023). "IL-11 is involved in the induction of pulmonary fibrosis in lung diseases." (PMID 36755348, 2023). "IL-11 promotes lung fibroblast activation and transformation into myofibroblasts as well as the alveolar epithelial to mesenchymal transition promoting extracellular matrix accumulation, as well as lung fibrosis when was administered in mice." (PMID 36376885, 2022). "Our finding is consistent with recent research that revealed the prominent role of IL-11 signaling in pulmonary fibrosis pathology, suggesting that IL-11 could serve as a potential drug target for the treatment of lung fibrosis and IPF." (PMID 35731866, 2022). "Following bleomycin-induced lung injury, Il11−/− mice are protected from pulmonary fibrosis and exhibit lesser ERK, STAT3 and NF-kB activation, reduced Il1b, Timp1, Ccl2 and diminished IL6 expression, both at baseline and after injury: placing Il11 activity upstream of IL6 in this model." (PMID 34239012, 2021).
pulmonary fibrosis (continued). "Anti-IL11 treatment blocks the Erk and Smad pathways to inhibit the activation of lung fibroblasts, thereby alleviating lung inflammation and reversing bleomycin-induced pulmonary fibrosis." (PMID 34853322, 2021). "Notably, STAT3 activation was unaffected and therefore appears to be tangential to IL-11-mediated lung fibrosis." (PMID 33262481, 2020). "Antibody therapies targeting IL-11 can reduce pulmonary fibrosis and inflammation in mice." (PMID 33262481, 2020). "In addition, various evidences have point out an important role for IL-6 and IL-11 in the pulmonary fibrosis." (PMID 15955252, 2005). "Hence, anti-IL11 therapeutics, which are advancing towards clinical trials in patients with PF, may promote alveolar regeneration and mitigate lung fibrosis that would differentiate anti-IL11 therapy from anti-fibrotics currently used in the clinic." (PMID 39358385, 2024). "However, little is known about the involvement of IL11 in lung fibrosis in COVID-19 disease." (PMID 37545510, 2023). "Interleukin-11 (IL-11) is a profibrotic cytokine essential for the differentiation of fibroblasts into collagen-secreting, actin alpha 2, smooth muscle–positive (ACTA2+) myofibroblasts, driving processes underlying the pathogenesis of idiopathic pulmonary fibrosis (IPF)." (PMID 35731866, 2022). "Therefore, the down-regulation of IL-11 might be a potential therapeutic approach for the treatment of pulmonary fibrosis." (PMID 35731866, 2022). "In addition, a growing body of evidence has confirmed that IL-11 is an essential mediator in a variety of inflammatory or autoimmune diseases including idiopathic pulmonary fibrosis, renovascular hypertension, nonalcoholic steatohepatitis, and systemic sclerosis." (PMID 35273577, 2022). "IL-11 contributes to the development of fibrosis and inflammation in TED, and its parallel targeting in pulmonary fibrosis further underscores its potential as a therapeutic target in TED." (PMID 40807149, 2025). "In this study, we show that IL11 is uniquely expressed by aberrant basaloid and KRT5-/KRT17+ cells in human lung fibrosis and by Krt8+ transitional cells in the fibrotic lungs of mice after bleomycin injury." (PMID 39358385, 2024). "One study suggested that TGF-β1, produced by fibroblasts, and its downstream factor interleukin (IL)-11 can promote peripheral AT2 cell aging and exacerbate pulmonary fibrosis." (PMID 38625722, 2024). "Other drugs, such as pirfenidone, which targets TGFβ1, and lademirsen, which targets miR21, and pulmonary fibrosis drugs, such as nintedanib, PRM-151, epigallocatechin gallate, ziritaxestat, trametinib (MEK inhibitor), and anti–IL-11 antibody, are under study." (PMID 37831322, 2023). "IL11 is presumably more than just a biomarker as IL11 plays a central role in mediating the fibrotic activity of TGF-β, for instance, in cardiovascular and pulmonary fibrosis as well as systemic sclerosis, non-alcoholic steatohepatitis, and kidney dysfunction." (PMID 38003371, 2023). "In combination with an unbiased proteomic approach, we were able to identify important mediators that translate these effects such as IL11, one of the top 15 proteins with increased abundance in ILD, in our study referring to cases of pulmonary fibrosis." (PMID 37266432, 2023). "With respect to interleukins and cytokines, interleukin 11 (IL-11) is increased in the AH in POAG and upregulated in other fibrotic diseases such as idiopathic pulmonary fibrosis and furthermore administration of IL-11 can induce lung fibrosis." (PMID 36421707, 2022). "We then examined the expression of IL-11 and ACTA2 in lung sections from IPF patients and the mouse model of bleomycin-induced pulmonary fibrosis." (PMID 35731866, 2022). "IL11 expression is elevated in the mouse lung after bleomycin (BLM)-induced injury and BLM-induced lung fibrosis is attenuated in Il11ra1−/− mice." (PMID 34239012, 2021).
pulmonary fibrosis (continued). "Deletion of IL11 effectively reduced fibrosis in mutant organoids, suggesting that IL-11 is a therapeutic target in HPS patients suffering from lung fibrosis." (PMID 33262481, 2020). "Released nintedanib and IL‐11 siRNA synergistically inhibit fibroblast activation and ECM deposition, promote epithelium repair, and remodel the immune microenvironment, notably improving pulmonary fibrosis." (PMID 41211661, 2025). "Together these studies identified IL11 secretion from stromal cells as an important for fibrosis in patients with IPF, in lung organoids from patients with HPS and in mice with bleomycin-induced lung fibrosis." (PMID 38054591, 2023). "First, a significant up-regulation of IL-11 and actin alpha 2, smooth muscle (ACTA2) in lung tissues from both IPF patients and the mouse model of bleomycin-induced pulmonary fibrosis was observed, and a strong correlation was identified by quantitative analysis of the immunohistochemistry images." (PMID 35731866, 2022). "Several studies have shown that IL-11 is a regulatory target of TGF-β1: upregulation of IL-11 contributes to the activation of myofibroblasts, which is a crucial profibrotic pathway in cardiac fibrosis, pulmonary fibrosis, and liver fibrosis." (PMID 35273577, 2022). "Similar to CTGF, it is IL11 and NOX4 that are regulated by PPP lysates that mediate the effects of TGF-β on cardiovascular and liver fibrosis, and acute kidney injury and pulmonary fibrosis, respectively." (PMID 32781631, 2020). "Although the Ashcroft score from the lung tissues of the bleomycin-treated mice increased, which is indicative of lung fibrosis development, no statistically significant increase in IL11 mRNA levels was observed during the early (day 7) or late stages (day 21) of bleomycin administration." (PMID 38455057, 2024).